TSPO (translocator protein)
Diseases named in the same sentence as TSPO in open-access papers (continued):
Sharing a sentence is not in itself a finding about the gene and the disease.
glioma (continued). "Knockout of TSPO in glioma cell increased glioma growth and angiogenesis by promoting glycolysis and reducing oxidative phosphorylation, indicating its role in controlling the metabolic balance during tumor growth and angiogenesis." (PMID 37407961, 2023). "The TSPO expression evaluation in three F98 rat glioma models were 13.95, 23.07, and 11.09, respectively, by using the 2-ΔΔCT method." (PMID 36831378, 2023). "Our findings with gliomas are in line with previous studies proposing an immunomodulatory role for TSPO in the central nervous system." (PMID 38162485, 2023). "In this study, the cellular level uptake of DPA-BSTPG was found to be superior to those of BPA and BSH in F98 and C6 rat glioma cells, revealing the potential for drug delivery by targeting TSPO." (PMID 36831378, 2023). "The majority of studies had neuropathology as a reference, also encompassing histochemical analysis for determining TSPO expression on glioma and glioma-infiltrating cells." (PMID 37238297, 2023). "Western blots of glioma cells revealed a decrease of the antibody-binding signal in the transient TSPO-knockdown and a single band at the expected TSPO size (18 kDa)." (PMID 37697350, 2023). "As another example, ACKR3, which is only downregulated in TSPO-deficient BTIC129, prevents TMZ-induced apoptosis in glioma." (PMID 37158962, 2023). "TSPO PET results were useful to identify anaplastic transformation in gliomas and for the prognostic stratification of patients bearing homogeneous genetic alterations." (PMID 37238297, 2023). "Imaging results were correlated with glioma neuropathological assessment, encompassing the histochemical determination of TSPO expression on glial and tumor cells in specimens obtained after surgery or stereotactic biopsy." (PMID 37238297, 2023). "The potential of TSPO PET for the in vivo imaging of glioma TME was investigated by Zinnhardt and colleagues." (PMID 37238297, 2023). "Preliminary in vivo studies or case reports using TSPO imaging in glioma were promising, revealing high tumoral tracer uptake, especially in glioblastoma." (PMID 37536737, 2023). "In other words, the feasibility of the TSPO-targeted BNCT experiment using the F98 rat glioma model was proven." (PMID 36831378, 2023). "TSPO is frequently overexpressed in glioma, and a possible connection between TSPO enrichment and high malignancy has been suggested." (PMID 37697350, 2023). "TSPO PET provides the unique opportunity to explore glioma and its TME, thus paving the ground for patients’ selection for molecularly targeted therapies." (PMID 37238297, 2023). "The value of TSPO imaging in glioma was already determined in prognostication and detection of tumor heterogeneity." (PMID 36325388, 2022). "In sum, TSPO PET imaging in glioma mouse models remains an exciting field harboring the perspective of better understanding the glioblastoma microenvironment at a molecular level." (PMID 35453488, 2022). "It is this advance that has recently lead to reports of TSPO PET radiotracers as suitable options for the characterization of gliomas at initial diagnosis." (PMID 35303961, 2022). "Specifically, the authors compared the TSPO radioligand uptake in PET from wildtype GL261 glioma in TSPO KO mice with the uptake of wildtype GL261 glioma in wildtype host tissue (TSPO+/+)." (PMID 35453488, 2022). "Several preclinical and clinical trials have observed a high expression of the 18 kDa translocator protein (TSPO) in adult gliomas compared to the low TSPO expression in healthy brain regions." (PMID 36293329, 2022). "TSPO expression is not only specific to the glioma cells but can be highly expressed after glial cell activation, especially in activated microglial cells and reactive astrocytes." (PMID 36293329, 2022).
glioma (continued). "In furtherstudies, 77 dissipated the mitochondrial membrane andinhibited glioma cells through an intracellular pro-apoptotic mechanisminduced by TSPO." (PMID 35786935, 2022). "TSPO is not only expressed in myeloid cells of the tumor microenvironment (TME) but also in tumor cells in dependence of the glioma grade." (PMID 36325388, 2022). "In conclusion, ceCT and TSPO-PET derived lesion volumes should probably be considered as complementary glioma biomarkers." (PMID 36325388, 2022). "Although amino-acid radiotracers have been increasingly studied in neuro-oncology, TSPO imaging seems to be particularly promising because it identifies glioma physio-pathological mechanisms that are distinct from those invoked by amino-acid tracers." (PMID 35303961, 2022). "In years, the 18 kDa translocator protein (TSPO) emerged as an important imaging target in glioma and the in vivo detection of TSPO is feasible with positron emission tomography (PET) and single photon emission computed tomography (SPECT) ligands." (PMID 36325388, 2022). "In the wake of its recognition as a functionally relevant target in GBM, increasing experience has recently been obtained with glioma imaging directed against TSPO, including the use of PET tracers such as [18F]GE-180, [18F]DPA-714, [18F]PBR111 and [18F]VC701." (PMID 35453488, 2022). "Within the LABs, the frontoparietal SUV as a potential pseudo-reference tissue for glioma TSPO-PET imaging was similar between patients with glioma and the controls (p = 0.599)." (PMID 34073557, 2021). "TSPO has been found to be involved in the regulation of cell proliferation and apoptosis in gliomas, which are highly aggressive malignant tumors with a poor prognosis." (PMID 33917344, 2021). "To investigate the association between TSPO mRNA expression and OS time in GBM patients, we interrogated a series of independent datasets (the Chinese glioma genome atlas (CGGA), TCGA-GBM using Affymetrix HG-U133A platform, and Gravendeel)." (PMID 34572751, 2021). "Recent studies of TSPO-PET in conjunction with in-depth immunophenotyping suggested [18F]DPA-714 to non-invasively image the degree and heterogeneity of the glioma-associated immunosuppressive tumor microenvironment (TME) in vivo." (PMID 33500706, 2021). "Similar results were obtained for cerebellar SUVs, which can be applied as a pseudo-reference tissue for TSPO-PET imaging of patients with glioma and neurodegenerative diseases." (PMID 34073557, 2021). "Patient 3, who had low-grade gliomas in the right lateral temporal area, showed TSPO radioligand uptake in the tumor and in the right hippocampus." (PMID 33407581, 2021). "Many researchers have reported that TSPO expression is increased in various types of cancer, including brain tumors and gliomas." (PMID 33917344, 2021). "In Glioblastoma (GBM), the most malignant primary brain tumor, TSPO expression levels are strongly elevated and scientific evidence accumulates, hinting at a pivotal role of TSPO in tumorigenesis and glioma progression." (PMID 33066460, 2020). "Our recent studies have shown that mitochondria isolated from TSPO knockdown glioma cells were unable to accumulate and retain the same amounts of Ca2+ (before mPTP opening) as mitochondria isolated from wild-type glioma C6." (PMID 32722345, 2020). "In contrast, in TSPO−/− animals bearing the diffusely infiltrating wild-type glioma, the [18 F]PBR111 retention and signal was restricted to the tumour volume without any appreciable signal in the Tspo−/− host tissue." (PMID 32561881, 2020). "Pre-clinical studies using TSPO PET ligands for in vivo imaging of gliomas revealed promising results, which were corroborated in humans by first-generation PET-tracers such as 11C-PK11195." (PMID 33066460, 2020). "In view of these findings, further studies are needed to elucidate the role of TSPO as a modulator of steroid synthesis in affecting the development and proliferation of glioma." (PMID 33066460, 2020).
glioma (continued). "To further dissect the link between circadian neurosteroid synthesis and mitochondrial dynamics, we disturbed mitochondrial fusion/fission activity and determined P5 and TSPO levels over time in synchronized A172 glioma cells." (PMID 33086741, 2020). "In the C6 rat glioma cell line, the overexpression of TSPO increased the ability to overcome contact-dependent inhibition of cell growth." (PMID 33066460, 2020). "The expression of this protein is also elevated in several cancers: colon, breast, glioma, prostate, colorectal, liver and ovary cancer, relating TSPO with disease progression and survival." (PMID 32283680, 2020). "The PET ligand [11C]PK11195 was one of the first ligands evaluated for TSPO expression in glioma patients." (PMID 32213992, 2020). "Knockout of TSPO with the CRISPR/Cas9 system in mouse GL261 glioma cells resulted in increased proliferation and viability in comparison to wild type cells." (PMID 33066460, 2020). "This suggestion was confirmed during our experiments with TSPO-knockdown glioma c6 cells (unpublished data)." (PMID 32370072, 2020). "Early on, the strong potential of TSPO as a non-invasive marker in glioma was recognized, based on its overexpression in tumors compared to the normal brain." (PMID 33066460, 2020). "TSPO knockout in a glioma animal model as well as in patient-derived cells resulted in increased mitochondrial fragmentation, reduced ATP production, and decreased mitochondrial oxidative phosphorylation." (PMID 33066460, 2020). "TSPO knockout glioma cells were shown to have more mitochondrial fragmentation, increased levels of mitochondrial fission proteins such as FIS1, and decreased complex I activity compared to wildtype cells." (PMID 32102369, 2020). "By following [18F]DPA-714 uptake, TSPO was shown to be highly expressed in glioma cell lines and tumors." (PMID 31661894, 2019). "As one of the few TAM-focusing studies, Zinnhardt and colleagues identified specific compartments along mouse glioma margins with enhanced TSPO-specific 18F-DPA-714 uptake." (PMID 31695797, 2019). "Of note, the genetic knockdown of TSPO in human U118MG glioma cell line resulted in mitochondrial PPIX accumulation upon exposure of cells to PPIX, suggesting a role of TSPO in preventing intracellular accumulation of PPIX." (PMID 29875327, 2018). "Many investigators reported that TSPO expression increases in different types of cancer, including brain tumor and glioma." (PMID 30248940, 2018). "It has been established that TSPO is involved in the regulation of cellular proliferation and apoptosis in gliomas, which are highly aggressive malignant cancers with a poor prognosis." (PMID 30248940, 2018). "There is evidence indicating that a decrease in TSPO expression is accompanied by an increase in the level of CNPase in mitochondria that are isolated from glioma C6 with TSPO knockdown [in press]." (PMID 30248940, 2018). "New PET radiopharmaceuticals have been developed to detect the 18 kDa translocator protein TSPO which is expressed by most glioma cells and activated microglia." (PMID 29348889, 2017). "TSPO is upregulated in neuroinflammation and its overexpression has been proved in several types of cancers, including gliomas, whereas expression in the healthy brain is low." (PMID 27322261, 2016). "The cytotoxicity of prepared conjugates was evaluated on MTX-sensitive human and rat glioma cell lines overexpressing TSPO." (PMID 27322261, 2016). "TSPO ligand-MTX conjugates have shown to possess a high binding affinity for TSPO, with IC50 values ranging from 7.2 to 40.3 nM, and exhibited marked toxicity against glioma cells overexpressing TSPO, in comparison with the parent drug MTX." (PMID 27322261, 2016). "These foundational studies demonstrated the utility of [11C](R)-N-methyl-N-(1-methylpropyl)-1-(2-chlorophenyl)-isoquinoline-3-carboxamide ([11C]PK11195) as a radiotracer for targeted PET imaging of TSPO within glioma." (PMID 26517124, 2015).
glioma (continued). "The objective of this preliminary study was to evaluate the correlation between TSPO expression and glioma grade (low, high) in clinical samples, and to explore the utility of [18F]PBR06 to assess TSPO expression in a clinically relevant rat glioma model." (PMID 26517124, 2015). "In the current study, we demonstrate by immunohistochemical staining that TSPO is highly expressed in human glioma and correlates with grade." (PMID 26517124, 2015). "The preclinical studies reported herein suggest that TSPO represents a promising target in human glioma imaging for detection, staging, and therapy." (PMID 26517124, 2015). "Several studies have investigated the expression of the TSPO protein levels in colorectal malignancies, meningiomas, glioma, glioblastoma, hepatocellular carcinoma, melanoma, and breast cancer, indicating that TSPO could play a role these cancers." (PMID 40550494, 2025). "Translocator protein (TSPO) ligands for positron emission tomography (PET) imaging have demonstrated glial pathology initiated by gliomas and metastases by demonstrating widespread microglial activation in the OFC, mPFC, and ACC, all of which are critically important to personality regulation." (PMID 40943040, 2025). "The stereotactic inoculation process in orthotopic glioma mouse models is highly invasive and therefore represents a relevant inflammatory driver, which thus might interfere with the interpretability of TSPO PET data obtained in these models." (PMID 38255293, 2024). "A total of 344 patients presenting with glioma that received TSPO-PET imaging were screened." (PMID 39150564, 2024). "This main finding of our study was obtained after careful selection of a cohort only consisting of newly diagnosed patients with glioma that underwent TSPO-PET imaging prior to any intervention, since therapy regimes such as radiochemotherapy or surgery cause inflammatory responses in brain." (PMID 39150564, 2024). "Similarly, TSPO knockout in mouse GL261 glioma cells resulted in mitochondrial fragmentation, whereas wild-type cells contained more fused or elongated mitochondria." (PMID 39684592, 2024). "In clinical glioma studies, TSPO radioligand uptake in PET regularly exceeded [18F]FET uptake." (PMID 38255293, 2024). "Furthermore, TSPO overexpression has been found in certain cancerous conditions, including breast and colorectal cancer, glioma and hepatocellular carcinoma." (PMID 39275061, 2024). "Similarly, TSPO knockout murine glioma cells and TSPO knockdown human microglial cells displayed significantly higher cytosolic ROS levels than wild-type cells." (PMID 39684592, 2024). "It has been suggested that TSPO levels may be correlated with the metastatic potential of breast cancer and gliomas." (PMID 39275061, 2024). "TSPO-deficient mouse glioma cells also showed a marked reduction in MFN1 levels and no change in DRP1 protein expression." (PMID 39684592, 2024). "Furthermore, a human TSPO PET scan of a glioma patient after stereotactic biopsy is presented in a translational perspective." (PMID 38255293, 2024). "In conclusion, our study improves the understanding of TSPO as an imaging marker in gliomas." (PMID 37697350, 2023). "In vitro competition binding assays showed that [18F]BIBD-239 has high affinity to TSPO, and animal models of stroke and glioma showed high and displaceable uptake in the lesions, although no significant displacement was observed in the healthy areas of the rat brain." (PMID 37249618, 2023). "As a result, an F98 rat glioma model was shown to be suitable for experiments targeting TSPO." (PMID 36831378, 2023). "In glioblastomas/IDH-wildtype gliomas the TSPO promotor was equally unmethylated as in the non-neoplastic controls and we neither observed TSPO gene amplifications nor TSPO gain of function mutations." (PMID 37697350, 2023).
glioma (continued). "In summary, TSPO transcriptional regulation in gliomas might be the result of a complex interplay between changes in TSPO promotor methylation and their effects on transcription factor binding." (PMID 37697350, 2023). "TSPO is overexpressed in activated microglia and macrophages, but also in glioma cells." (PMID 37509252, 2023). "It is also known that IDH-mutant gliomas commonly exhibit a genome-wide hypermethylation phenotype and the observed TSPO hypermethylation might be part of this." (PMID 37697350, 2023). "In this perspective, TSPO might represent a valuable biomarker for simultaneously assessing glioma biological characteristics as well as having insight into the glioma-associated tumor microenvironment (TME)." (PMID 37238297, 2023). "Since TSPO expression was confirmed in the F98 rat glioma model, DPA-BSTPG, which was developed to target TSPO, could be administered using CED to deliver boron to the tumor." (PMID 36831378, 2023). "To explore alternative regulatory mechanisms of TSPO expression we further analyzed large DNA-based glioma data sets (in total 531 samples) in cBioportal but neither detected any relevant TSPO coding mutations nor TSPO gene amplifications (data not shown)." (PMID 37697350, 2023). "We used in silico data to get an overview of TSPO expression in low- and high-grade gliomas." (PMID 37697350, 2023). "In the most recent report, PET with TSPO can even predict the prognosis of glioma patients." (PMID 36831378, 2023). "The TSPO, which has been shown to be expressed in the C6 rat glioma bearing brain tumor model and 9L rat glioma bearing brain tumor model, was also confirmed in the F98 rat glioma model." (PMID 36831378, 2023). "Moreover, PET with TSPO even has the potential to predict the prognosis of patients with recurrent gliomas." (PMID 36831378, 2023). "It was found that the higher the TSPO expression, the higher the severity of gliomas." (PMID 37627119, 2023). "Moreover, positron emission tomography (PET) studies with TSPO were able to predict the prognosis of patients with recurrent gliomas." (PMID 37627119, 2023). "Thus, the highest overall TSPO signals were observed in the solid tumor core regions with a high glial tumor cell content." (PMID 37697350, 2023). "A potential prognostic relevance of TSPO in glioma was proposed more than 25 y ago." (PMID 37536737, 2023). "Regarding TSPO regulation, initial in silico analyses and confirmation on an own cryo-conserved tissue collective established a role for TSPO promotor hypermethylation in the reduction of TSPO expression levels in the molecularly defined subgroup of IDH-mutant gliomas." (PMID 37697350, 2023). "The aim of this present systematic review is to provide a comprehensive overview of the existing literature concerning the clinical applications of PET with TSPO ligands (i.e., TSPO PET) for glioma imaging, also trying to delineate the next steps for its implementation in clinical practice." (PMID 37238297, 2023). "Therefore, the exact composition and function of these TSPO proteins in glioma should be further explored." (PMID 36278207, 2022). "We explored the role of TSPO in glioma by targeting it with the synthetic ligand XBD173." (PMID 36278207, 2022). "TSPO signaling clearly exceeded the FET signal, which might indicate the activation of glioma-associated myeloid cells beyond the tumor borders delineated by FET-PET." (PMID 35158809, 2022). "A first study has used TSPO PET imaging in glioma using a TSPO knock out (KO) mouse strain, which might also be a promising tool to further decipher the origin of TSPO-related molecular processes in glioblastoma." (PMID 35453488, 2022). "Ultimately, TSPO agonists or antagonists could also act as direct modulators of TSPO expression in gliomas and such therapies would profit from monitoring of altered target expression by TSPO-PET." (PMID 36325388, 2022). "TSPO expression in glioma is correlated with the grade of malignancy and survival." (PMID 36278207, 2022).